RNA5-8SN3 (RNA, 5.8S ribosomal N3)
Gene: Ribosomal RNA gene on chromosome 21 (8,395,607 to 8,395,759, forward strand). Ensembl gene ENSG00000275215.
Gene Ontology:
Molecular function: structural constituent of ribosome
Cellular component: ribosome
Homologues: Orthologues: chimpanzee 5_8S_rRNA (100% identical), macaque 5_8S_rRNA (100% identical), rabbit 5_8S_rRNA (100% identical), rat 5_8S_rRNA (100% identical). Paralogues in human: 5_8S_rRNA (100% identical), RNA5-8SN1 (100% identical), RNA5-8SN2 (100% identical), RNA5-8SN4 (100% identical), RNA5-8SN5 (100% identical), 5_8S_rRNA (90% identical), 5_8S_rRNA (87% identical), 5_8S_rRNA (86% identical).